MTRFR (mitochondrial translation release factor in rescue)
Description:
Part of a mitoribosome-associated quality control pathway that prevents aberrant translation by responding to interruptions during elongation. As heterodimer with MTRES1, ejects the unfinished nascent chain and peptidyl transfer RNA (tRNA), respectively, from stalled ribosomes. Recruitment of mitoribosome biogenesis factors to these quality control intermediates suggests additional roles for MTRES1 and MTRF during mitoribosome rescue.
Synonyms: C12orf65; FLJ38663; SPG55; COXPD7; mtRF-R
Tractability: Small molecule: a structure with a bound ligand is known. PROTAC: ubiquitination databases record sites on it.
Gene: Protein-coding gene on chromosome 12 (123,232,142 to 123,258,079, forward strand). Ensembl gene ENSG00000130921.
Subcellular location: Mitochondrion
Subcellular location (Human Protein Atlas): Cytosol; Nucleoplasm; Mitochondria
Pathways (Reactome):
Metabolism of proteins: Mitochondrial ribosome-associated quality control
Gene Ontology:
Molecular function: protein binding; ribosomal large subunit binding; tRNA binding; peptidyl-tRNA hydrolase activity; translation release factor activity
Biological process: mitochondrial translational termination; translational termination
Cellular component: mitochondrion; mitochondrial matrix
Genetic constraint (gnomAD): Loss-of-function variants: 13 observed, 16.88 expected, observed/expected ratio (o/e) 0.77, 90% interval 0.5 to 1.22. The upper end of that interval is the gene's LOEUF score, 1.22, which puts it in group 5 of 6, group 1 being the genes least tolerant of losing a copy. Missense variants: 196 observed, 207.66 expected, observed/expected ratio (o/e) 0.94, 90% interval 0.84 to 1.06. Synonymous variants: 77 observed, 83.24 expected, observed/expected ratio (o/e) 0.93, 90% interval 0.77 to 1.12.
Gene-disease validity (ClinGen):
ClinGen rates the evidence that MTRFR causes each of these diseases.
Leigh syndrome (autosomal recessive): Definitive. A progressive neurological disease defined by specific neuropathological features associating brainstem and basal ganglia lesions.
mitochondrial disease (autosomal recessive): Definitive.
Homologues: Orthologues: chimpanzee MTRFR (98% identical), macaque MTRFR (96% identical), pig MTRFR (83% identical), rabbit MTRFR (78% identical), dog MTRFR (77% identical), mouse Mtrfr (77% identical), rat Mtrfr (77% identical), guinea pig MTRFR (77% identical), tropical clawed frog mtrfr (58% identical), zebrafish mtrfr (47% identical), Drosophila melanogaster CG30100 (34% identical).
Diseases named in the same sentence as MTRFR in open-access papers:
MTRFR is named in the same sentence as 23 diseases in open-access papers, as found by Europe PMC text mining. Sharing a sentence is not in itself a finding about the gene and the disease. The quoted sentences say what the papers report.
optic atrophy (7 papers, 2014 to 2025). A disorder characterized by loss of optic nerve fibers. "MTRFR deficiency is characterized by a wide range of phenotypes based on the mutations; the three primary clinical features are optic atrophy, peripheral neuropathy, and spastic paraplegia." (PMID 40376928, 2025). "Homozygosity mapping was used to identify mutations in MTRFR in two patients who developed Leigh syndrome, optic atrophy, and ophthalmoplegia." (PMID 34277617, 2021). "Other groups identified a novel protein-truncating mutation in the MTRFR gene in a family with neuropathy and optic atrophy." (PMID 34277617, 2021). "Another group reported that a compound heterozygous mutation of MTRFR caused distal motor neuropathy and optic atrophy in a Chinese patient." (PMID 34277617, 2021). "MTRFR participates in the process of mitochondrial translation and is related to multiple phenotypes, including early onset optic atrophy, progressive encephalomyopathy, peripheral neuropathy, and spastic paraparesis." (PMID 34277617, 2021).
Leigh syndrome (5 papers, 2014 to 2025). "Recessive pathogenic variations in MTRFR cause rare mitochondrial disorders described as Behr's syndrome, Leigh syndrome and Charcot-Marie-Tooth disease type 6 (CMT6), often including optic and peripheral neuropathy." (PMID 40452409, 2025). "A homozygous nonsense mutation of MTRFR (NM_001143905:c.346delG, p.Val116∗) was described in a pair of female twins diagnosed with Leigh syndrome." (PMID 34277617, 2021). "When MTRFR is deficient or mutated, mitochondrial translation remains stalled, leading to a severe and disabling neurological disease with spastic paraparesis, optic and peripheral neuropathy diagnosed as Behr's syndrome, Leigh syndrome and CMT6." (PMID 40452409, 2025). "For diseases like MTRFR deficiency, AAVs can target the multiple cell types associated with the disease and have been used in related disorders such as Leber's congenital amaurosis (LCA), dominant optic atrophy (DOA) and other mitochondrial disorders like Leigh syndrome." (PMID 40452409, 2025). "Like Leigh syndrome and DOA, MTRFR deficiencies are a good candidate for gene therapy treatment, and our studies have shown that we are able to get adequate expression in various organs without adverse effects of the MTRFR transgenes." (PMID 40452409, 2025).
Behr syndrome (3 papers, 2018 to 2025). A disorder characterized by early-onset optic atrophy along with neurological features, including ataxia, spasticity, and intellectual disability. "Rare recessive diseases, like Behr's syndrome and MTRFR deficiency stemming from MTRFR variants, tend to be good candidates for gene replacement therapies such as adeno-associated virus (AAV) delivery of rescuing wild-type complementary DNAs (cDNAs)." (PMID 40452409, 2025).
Intellectual disability (2 papers, 2020 to 2025). "Clinical clues to pinpoint the causative gene from the heterogeneous CMT2 and AR‐CMT2 group included pyramidal signs in SACS, MTRFR, and HSPB1, vocal cord paralysis in TRPV4, intellectual disability in MCM3AP, late disease onset in MME, in accordance with previous reports." (PMID 39776111, 2025).
mitochondrial encephalomyopathy (1 paper, 2025). A heterogenous group of disorders characterized by alterations of mitochondrial metabolism that result in muscle and nervous system dysfunction. "C12orf65, a second rescue factor, began with a report describing that loss‐of‐function mutations in a nuclear gene, MTRFR, in two unrelated pedigrees lead to mitochondrial encephalomyopathy." (PMID 40376928, 2025).
Optic neuropathy (1 paper, 2025). "However, we also looked specifically for possible peripheral nerve histopathology and optic neuropathy phenotypes, as these are key features of patients with MTRFR deficiency." (PMID 40452409, 2025). "An analogous approach could be feasible for treating the optic neuropathy associated with MTRFR deficiency; however, delivery directly to the eye would not treat the peripheral neuropathy and other symptoms of MTRFR deficiency." (PMID 40452409, 2025).
peripheral neuropathy (4 papers, 2020 to 2025). A disorder affecting the peripheral nervous system. "This, in conjunction with our work on cell-based models of MTRFR deficiency, including engineered hiPSC lines with a patient-associated early truncation, will allow us to uncover more about the mechanisms driving this inherited peripheral neuropathy." (PMID 40452409, 2025).
mitochondrial disease (3 papers, 2021 to 2025). "All the heterozygous knockout lines appeared normal, consistent with the fact that in humans, the mitochondrial disease, COXPD7, resulting from loss‐of‐function mutations in MTRFR is inherited in an autosomal recessive manner." (PMID 40376928, 2025). "Such a functional complementarity is not observed in the human counterparts, since ICT1 deletion is lethal, while that of MTRFR causes mitochondrial diseases." (PMID 40376928, 2025). "Although loss‐of‐function mutations in MTRFR have been linked to human mitochondrial diseases, data on this association in other vertebrates are lacking." (PMID 40376928, 2025).
genetic diseases (2 papers, 2025). "PMDs include genetic disorders that are caused by pathogenic variants in genes that code for or are associated with the mitochondrial respiratory chain, such as MTRFR deficiency." (PMID 40452409, 2025). "Creating vertebrate models with MTRFR dysfunction will help to facilitate research and drug development for rare genetic diseases, such as COXPD7." (PMID 40376928, 2025).
MTRFR also shares sentences with these, for which no sentence is quoted: Spastic paraparesis (5 papers); autosomal recessive spastic paraplegia 55 (2); encephalomyopathy (2); neuropathy (2); Ataxia (1); axonal neuropathy (1); Charcot-Marie-Tooth disease type 6 (1); Cognitive impairment (1); Leber congenital amaurosis (1); ophthalmoplegia (1); retinal degeneration (1); schizophrenia (1); Spastic paraplegia (1); Vocal cord paralysis (1).